IL4 (interleukin 4)
Diseases named in the same sentence as IL4 in open-access papers (continued):
Sharing a sentence is not in itself a finding about the gene and the disease.
asthma (continued). "In the ovalbumin-induced rat asthma model, FXR reduces airway inflammation by preventing inflammatory cell infiltration and inhibiting IL-4, IL-5, and IL-13 secretion, likely through antagonizing NFκB signaling and its target genes." (PMID 39411430, 2024). "Further research is needed to determine if pDCs have more roles in asthma beyond their known IFN-λ secretion, which counteracts IL-4’s impact on CD4+ T cells." (PMID 39530090, 2024). "Intranasal administration of PAO elicited characteristic features of asthma in WT mice, whereas TLR4-KO mice exhibited reduced asthma symptoms but sustained IL-4 levels." (PMID 37426425, 2023). "A recent study highlighted the major contributions of Th2 cytokines, such as IL4, IL13, and IL5, to asthma, while interferon-γ, a Th1 cytokine, has recently been shown to maintain the chronic inflammatory response in asthma." (PMID 37191813, 2023). "The changes of peripheral CD3−CD56+CD16+ NK cells proportions positively correlated with the IFN-γ/IL-4 and IFN-γ/IL-5 ratios on day 1 to day 3 in asthma subsequent to upper respiratory viral infections." (PMID 37865742, 2023). "There were significant differences in the distribution of the three genotype frequencies which including the gene loci ADRB2 rs1042713, IL4 rs2243250 and IL13 rs20541 between the asthma group and the control group." (PMID 38049812, 2023). "Biologics targeting IgE, IL-4, IL-5, IL-13, and TSLP are used for uncontrolled severe asthma; their targets are all mediators produced by cells in the microenvironment of ILC2s." (PMID 36941691, 2023). "T2 high asthma is characterized by reduced lung function, poor asthma control, increased IgE levels, increased responsiveness to ICS treatment and persistent eosinophilic inflammation mediated by cytokines such as IL-4, IL-5 and IL-13." (PMID 40980110, 2023). "Vitamin E and selenium have been shown to affect Th2 cytokines (IL-4, IL-5, and IL-13) as well as their upstream cytokines (IL-25 and IL-33), suggesting that they may be a beneficial treatment for the management of allergic diseases such as allergic rhinitis and asthma." (PMID 37513609, 2023). "In Type-2 high asthma, TFH cells control IgE synthesis by secreting IL-4 to allergen-specific B cells." (PMID 37377958, 2023). "We also detected levels of oxidative stress markers (MDA, CAT and SOD), and frequent inflammation cytokines (IL-4, IL-5 and IFN-γ) in IL-13-induced BEAS-2B cells and BALF fluid of asthma mice." (PMID 36788676, 2023). "The overexpression of Th2 cytokines, such as IL-4, and the reduced expression of Th1 cytokines, such as IFN-γ, are the main manifestations of a Th1/Th2 imbalance, which is the key mechanism of an asthma attack." (PMID 36717898, 2023). "Disorders of intestinal flora disorders can trigger various systemic chronic inflammatory conditions, and IL-4, IFN-γ, IL-17, and IL-10 are potentially correlated with the pathogenesis of asthma." (PMID 36636604, 2023). "Increased secretion of Th2-type cytokines, such as IL-4, IL-5, and IL-13, in the allergic airway results in increased recruitment of inflammatory cells and airway hyperresponsiveness, suggesting that airway inflammation may be related to the severity of asthma." (PMID 36717898, 2023). "Therefore, IL-4 and IL-13 levels may be potential predictors of asthma in children with wheezing." (PMID 37760982, 2023). "This treatment significantly decreased inflammation markers like monocyte chemotactic protein 1, IL-4 and IL-6 levels in both COPD and asthma patients." (PMID 38067515, 2023). "Long-term follow-up studies with larger participant cohorts are necessary to observe changes in vitamin D, IL-4, IL-10, and CD23+ levels and the development of asthma to explain and prove the effect of these variables on the incidence of bronchial asthma." (PMID 37760982, 2023). "SXCF treatment significantly reversed the abnormal upregulation of LMs induced by the asthma model, thereby reversing the changes of cytokines such as TNF-α and IL-4." (PMID 36937885, 2023).
asthma (continued). "In CRS, as in asthma, the activation of ILC-2 cells leads to the release of cytokines (Il-9, Il-4, Il-5, and IL-13) stimulating a Th-2 inflammatory response." (PMID 37108417, 2023). "In short, mast cell-fibroblast crosstalk results in cytokine release (e.g., IL-4, TGF-β) that ultimately upregulates collagen synthesis, an integral part of airway fibrosis in asthma." (PMID 36911735, 2023). "In vivo, Lok effectively protected mice from asthma, as evidenced by decreased histological damage and level of cytokines in BALF (IL-4, IL-13 and TGF-β1) by 17%–77%." (PMID 37655452, 2023). "The treatment also reversed the OVA-induced increase of IL-4, TNF-α, and decrease in IL-10 and IFN-γ in these mice, indicating its anti-inflammatory role in obese asthma." (PMID 37893170, 2023). "Dupilumab, a monoclonal antibody that inhibits the action of IL-4 and IL-13 by blocking the shared IL-4 receptor α subunit has been approved by the FDA for moderate–severe atopic dermatitis, asthma, and rhinosinusitis with nasal polyposis treatment." (PMID 37765327, 2023). "Regarding the inflammatory response, TNF-α, IL-1β, IL-6, GM-CSF, IL-8, IL-4, and IL-10 are involved in BA to alleviate COVID-19, ALI, PF, COPD, PAH, and asthma." (PMID 37007037, 2023). "They observed a reduction in the blood levels of IL-4, IL-5, IL-13, and monocyte chemoattractant protein-1 (MCP-1) and an improvement in bronchial hyperreactivity (BHR) and FEV1." (PMID 36873818, 2023). "In the present study, there was an increase in the inflammatory markers involved, such as IL-1β, IL-4, IL-5, IL-6, IL-10, IL-13, IL-17, IFN-γ, and TNF-α, in the experimental model of asthma-COPD overlap." (PMID 37511021, 2023). "In severe asthma, IL-4+/IL-17+ T-cells in BALF expressed higher IL-4 levels compared with IL-4+ T cells." (PMID 37199256, 2023). "In asthma, HMGB1 expression induces HSP expression through the TLR4 / MYD88 / NF-kB pathway, which eventually produces IL-4 and IL-13." (PMID 37422662, 2023). "A study has found that there were reduced levels of Th1 in asthma, which reduces the levels of certain Th1-secreted cytokines including IFN-γ, and elevated levels of Th2, which can produce large amounts of IL-4, IL-5, and IL-13." (PMID 36846048, 2023). "In CRS, as well as in asthma, the activation of ILC-2 cells leads to the release of cytokines (Il-9, Il-4, Il-5, and IL-13) that promote a Th-2 inflammatory response." (PMID 37947596, 2023). "Our results have confirmed that patients with asthma and obesity have increased levels of circulating inflammatory cytokines such as TNF-α, IL-2, IL-4, and IL-17a despite the basic anti-inflammatory therapy." (PMID 37367676, 2023). "We found that the mRNA expression levels of several inflammatory factors, such as IL-4, IL-5 and TNF-α, were significantly lower in the PP121 group than in the asthma group." (PMID 37936054, 2023). "Biologic agents targeting inflammatory cytokines, comprising anti-immunoglobulin (Ig)E and anti-interleukin (IL)-4/IL-13, IL-5, IL-5R, and thymic stromal lymphopoietin (TSLP) have emerged as promising treatment options for patients with severe asthma." (PMID 36845128, 2023). "IL-4 induces enhanced B-cell autophagy in asthmatic mice via IAK, which contributes to antigen presentation and anti-apoptosis and is involved in asthma pathogenesis." (PMID 37090692, 2023). "Numerous double-positive Th2/Th17 lymphocytes secreting large amounts of IL-4 and IL-17 have been detected in the BALF of patients with severe asthma." (PMID 38203353, 2023). "IL-4, IL-17, IFN-γ, and IL-10 are the representative secretion factors of Th1, Th2, Th17, and Treg cells in asthma." (PMID 36636604, 2023). "The IFN-γ/IL-4 and IFN-γ/IL-5 ratios of the asthma patients with AURVIs on day 1 were remarkably higher than those in asthma alone group." (PMID 37865742, 2023).
asthma (continued). "The IL-4/IL-13/STAT6 pathway induces expression of inflammatory chemokines such as CCL11, CXCL1, and CXCL3 and is a central pathway in the pathophysiology of asthma, especially airway hyperresponsiveness." (PMID 35281012, 2022). "In conclusion, guinea pigs exhibited symptoms of asthma after stimulation with 0.5% OVA solution, resulting in significant increases in factors such as IgE and IL-4 in the serum." (PMID 35399628, 2022). "The therapeutic treatment of asthma involves the use of corticosteroid inhalers, bronchodilators, leukotriene modifiers and anti-E, anti–IL5, anti–IL4/IL13 antibodies, coupled with lifestyle modifications to reduce the exposure to environmental allergens." (PMID 36264868, 2022). "Therapeutic approaches targeting IL-4, IL-5, and TNF-α through their selective inhibitors are under clinical trials in management of asthma." (PMID 38143476, 2022). "In Th2-high asthma, MAPK promotes Th2 cells to release IL-4, IL-5, and IL-13, stimulating IgE production, eosinophil recruitment, and airway hyperresponsiveness." (PMID 35447890, 2022). "IL-4, IL-5, and IL-13 in BALF were measured to be about 10 times greater following the induction of asthma by OVA as compared to normal mice." (PMID 36115955, 2022). "It is generally accepted that the Th2 cytokines such as IL-4 and IL-13 lead to allergic asthma phenotype, and studies have shown that OVA-induced asthma in mice is often accompanied by a significant increase in Th2 cytokine levels." (PMID 35281601, 2022). "Increased Th2 cell activity led to elevated IL-4 levels, and decreased Th1 cell activity led to decreased INF-γ levels, indicating altered immune responses in patients with asthma." (PMID 36311189, 2022). "IL‐4, IL‐5 and CCL26 were significantly higher in T2‐high‐FNS compared with both T2‐low asthma and healthy controls." (PMID 35579040, 2022). "In an experimental asthma rat model, CBD diminished airway inflammation and IL-4, IL-5, IL-13, IL-6, IL-7 and TNF-α serum levels, which contribute to fibrosis and asthma pathophysiologies." (PMID 36556483, 2022). "The levels of IL-4, IL-5, IL-13, IFN-γ, eotaxin, and IgE in the asthma group were significantly higher than those in the control group." (PMID 35990822, 2022). "CAD significantly decreased the content of TNF-α, IL-13, IL-4, IL-1β and IL-5 in the bronchoalveolar lavage fluid (BALF), IL-17, IL-6, and OVA-specific IgE in serum and increased serum IFN-γ in asthma mice." (PMID 36213326, 2022). "The major flavonodial compound in the extract (vitexin) was shown to reduce the levels of inflammatory cytokines such as IL4, IL5, and IL13 by 64%, 95%, and 65% in an induced asthma model at concentration of 1 mg/kg." (PMID 35050106, 2022). "Meanwhile, IL-4 and TNF-α values in both COPD and ACO were significantly higher than those in asthma." (PMID 36311545, 2022). "We demonstrated that PARP-1 regulates the expression of many genes whose products are crucial in asthma by controlling NF-κB nuclear trafficking and the fate of STAT6 following IL-4 or allergen exposure." (PMID 36348405, 2022). "In asthma, allergic airway inflammation is initiated by IL-33 signaling through ST2, leading to increased IL-4, IL-5, and IL-13 production and eosinophil infiltration." (PMID 35025767, 2022). "Naringin possess anti-asthmatic effect by inhibiting IL-4, improved IFN-γ, and suppressed both the formation of eosinophils and mucus overproduction in mice with OVA-induced asthma." (PMID 36249455, 2022). "In order to explore the relationship between the expression of IL1-RL1 in sputum supernatant of patients with asthma and type 2 inflammation, we analyzed the correlation between IL1-RL1 and Th2 inflammatory factors, such as IL-4, IL-5, IL-10 and IL-13." (PMID 35578178, 2022).
asthma (continued). "Therapies targeting mast cell mediators and/or their receptors, including monoclonal antibodies targeting IgE, IL-4/IL-13, IL-5/IL-5Rα, IL-4Rα, TSLP, and IL-33, have been found safe and effective in the treatment of different phenotypes of asthma." (PMID 36430941, 2022). "In general, the thickening of bronchiolar smooth muscles is a pathognomonic characteristic of asthma, which is mediated by a TH2 response, marked by elevated levels of IL4 and airway inflammation." (PMID 35740365, 2022). "It has been shown that plasma miR-206, IL-4, IL-13, and INF-γ has potential significance for prognosis of asthma-induced pulmonary arterial hypertension." (PMID 36459329, 2022). "Fourteen core targets including IL4, IFNG, and MMP9 were identified for the treatment of asthma by SYD." (PMID 36212941, 2022). "Oral administration of CSE (0.53 or 5.3 mg/kg) to rats reversed IL-4, -5, and TNF-α levels in both body fluids (serum and BAL) of animals in comparison to asthma group." (PMID 38143476, 2022). "The current results should prompt a thorough search for IL-4-expressing B cells in human BAL and biopsy material from patients with asthma or other allergic diseases." (PMID 35359977, 2022). "GLP-1 agonists were also found to decrease eosinophilic-mediated secretion of IL4, IL8, and IL13 in mice with asthma." (PMID 36457601, 2022). "Asthma is an inflammatory disease characterized by AHR, the production of Th2 inflammatory cytokines (IL-4, IL-5, and IL-13), and the increased infiltration of inflammatory cells into the airways that results from the activation of Th2 cells." (PMID 36311189, 2022). "The level of production of IgE, IL-4, IL-5, IL-13, and IFN-γ is related to the severity of asthmatic symptoms in T2 asthma." (PMID 36430662, 2022). "The complex pathogenesis of asthma and AD were better clarified in recent years, thus suggesting novel therapeutical strategies, such as anti-TSLP (tezepelumab) and anti-IL-4 (dupilumab) antibodies, respectively." (PMID 36364420, 2022). "Considering Th1 cells play an important role to downmodulate Th2 response in asthma, its main effector IFN-γ inhibits the production of IL-4 and reduces the number of eosinophils in BALF in asthma." (PMID 35281601, 2022). "The levels of TNF-α, TNFR2, and CCL-9 in the asthma model group increase, while the levels of IFN-γ, IL-1α, ICAM-1, and IL-4 increased in the Majie cataplasm group, especially IFN-γ and IL-1α." (PMID 35600943, 2022). "Since IL-4 modulates the synthesis of IgE and OVA was used to induce asthma, we also detected the OVA-specific IgE in BALF." (PMID 35281601, 2022). "Plasma miR-206, IL-4, IL-13, and INF-γ have been found to have potential prognostic value in asthma-induced pulmonary arterial hypertension." (PMID 36459329, 2022). "EWAS of childhood asthma using PMBCs from the participants in the Inner-City Asthma Consortium identified several asthma-related genes such as IL13, IL4, and RUNX3 with differentially methylated regions (DMRs)." (PMID 35055381, 2022). "Consistently, we detected IL-4, IL-5, IL-13, IL-25, IL-10, IL-33, and TSLP in induced sputum of asthma and proved a positive correlation between BIRC3 and these cytokines." (PMID 35287655, 2022). "The IL-4 level was higher in the ACO-a model than in mice with asthma and COPD, and the IL-13 level was higher in the asthma and ACO-a models than in the COPD and ACO-b models." (PMID 36474247, 2022). "IL4 and exhaled nitric oxide, combined with 8-isoprostane and interferon-gamma (IFN-ɤ), were effective markers for asthma control." (PMID 36140412, 2022). "To explore the relationship among the levels of IL-4, IL-25, and S100A12 in nasal lavage fluid in patients with AR, asthma, and asthma comorbid AR, we performed Spearman correlation coefficient tests." (PMID 35348596, 2022). "BAL IL‐4 and BAL IL‐5 were both increased in the high BAL IL‐13 group compared with the low IL‐13 severe asthma group." (PMID 33411348, 2021).
asthma (continued). "In an OVA-induced asthma mouse model, it decreased OVA-specific IgE and IL-4 levels in the serum, relieved airway remodeling, attenuated subepithelial collagen deposition and inhibited EMT process." (PMID 34804018, 2021). "This indicated a reduction in the Th2 effector subset after Smo-inhibitor treatment, as IL-4 is a key Th2 cytokine, and ST2 is an IL-33 receptor that is involved in the Th2 inflammatory response and asthma, which can also be used as a marker of Th2 identity." (PMID 34580585, 2021). "This is because it can decrease oxidative stress, serum levels of immunoglobulin E (IgE), IL4, transforming growth factor (TGF-β), and increase interferon-gamma (IFN-γ) and IL-10 in the OVA-induced asthma model." (PMID 33959015, 2021). "OVA stimulation increased the expressions of IL‐4 and TNF‐α and decreased the expressions of IL‐10 and IFN‐γ in the BALF and plasma, in obese asthma, while metformin reversed these changes." (PMID 33421348, 2021). "In this study, Co-Q10 treatment reduced main type 2 cytokines (IL-4, 5 and 13) and enhanced main type 1 cytokine (INF-γ) in asthma and rhinitis groups." (PMID 33743807, 2021). "The biomarkers suspected to be most indicative of asthma are related to inflammation (type 2) and are attributed to TH2-cytokines, IL-4, IL-5, and IL-13." (PMID 34712855, 2021). "CLCA1 is also one of the 6 genes (CLCA1, IL4, IL13, MMP12, TGFB1, TLR4) found in common between our KE genesets and the genesets proposed by Bosse24 for COPD and Poole27 for asthma." (PMID 33731770, 2021). "A study has shown that estrogen mediates Th2 mediated severe asthma by slight upregulation of the GATA-3 expression and IL-4 production." (PMID 35096261, 2021). "Given that the Th2 cytokines (IL-4 and IL-13) are reduced in the lungs of GRK2+/− mice, it is possible that GRK2 modulates T cell responses during asthma." (PMID 35386975, 2021). "miR-224 plays an inhibitory role in PM2.5-induced asthma by inhibiting Th17 and TLR2, resulting in reduced secretion of IL-17, IL-4, and IL-5." (PMID 34566492, 2021). "In the pathogenesis of asthma, CD4+ T cells synthesize proinflammatory cytokines such as IL-4, IL-5 and IL-13." (PMID 34209324, 2021). "Asthma is believed to be mediated by CD4+ T-lymphocytes, which produce type 2 cytokines including IL4 and IL5." (PMID 33918602, 2021). "The MSC-pANGPT1 (angiopoietin 1 gene) were aerosolized in a rabbit OVA-induced asthma and reduced the expression of pro-inflammatory cytokine genes (IL-4, TNF, TGF-β, and MMP-9), which can be an additional beneficial effect in asthma treatment." (PMID 33959015, 2021). "Increased release of Th2 cytokines mainly IL-4, IL-5, and IL-13 and decreased release of IFN-γ as a Th1 cytokine also contribute in the onset and progression of asthma." (PMID 34804178, 2021). "Of the cytokines produced by splenocytes, IL-4 and IL-5 decreased and IFN-γ increased, similar to the results in animal asthma models." (PMID 34635172, 2021). "The findings from the current investigation were comparable to those in earlier studies that induced asthma using a similar sensitization method which also confirmed animal sensitization with changes in IL-4, IFN-γ, and IFN-γ/IL-4 ratio." (PMID 34804178, 2021). "Th2 cytokines, such as IL‐4 or IL‐13, contribute to the development of inflammation in the lungs of OVA‐induced murine asthma model by promoting differentiation of macrophages into alternatively activated M2 macrophages." (PMID 33945658, 2021). "In 2013, BM-MSC infusion upregulated IL-12 levels and downregulated IL-4, IL-13, OVA-specific IgE, OVA-specific IgG1 and OVA-specific IgG2a levels in a mouse asthma model." (PMID 34635172, 2021). "Asthma is driven by group 2 innate lymphoid cells, antigen-specific CD4+ T helper type 2 cells and their cytokines such as interleukin (IL)-4, IL-5, IL-13." (PMID 34516405, 2021).